UHRF1 (ubiquitin like with PHD and ring finger domains 1)
Diseases named in the same sentence as UHRF1 in open-access papers (continued):
Sharing a sentence is not in itself a finding about the gene and the disease.
oncocytomas (1 paper, 2009). "Expression levels of UHRF1 in the oncocytomas and in normal kidney were not different statistically (P=0.9535)." (PMID 19491893, 2009).
oral cancer (1 paper, 2023). "UHRF1 expression increases in malignancies but its role in oral cancer and salivary gland malignancies remains understudied." (PMID 37887281, 2023).
osteoarthritis (1 paper, 2022). A noninflammatory degenerative joint disease occurring chiefly in older persons, characterized by degeneration of the articular cartilage, hypertrophy of bone at the margins and changes in the synovial membrane. "Analyses of NCBI’s Gene Expression Omnibus (GEO) database for gene expression (GSE89408) revealed that UHRF1 mRNA was also significantly upregulated in synovium from patients with RA compared with healthy individuals and patients with osteoarthritis (OA), which had similar UHRF1 mRNA levels." (PMID 35472067, 2022).
parasite infection (1 paper, 2020). "This is the first report demonstrating that a parasitic infection, via its kinase ROP16, activates a transcription factor, UHRF1, leading to an epigenetic regulation process." (PMID 31492965, 2020).
renal fibrosis (1 paper, 2025). A final common manifestation of a wide variety of chronic kidney diseases characterized by glomerulosclerosis and tubulointerstitial fibrosis. "We next aimed to explore the mechanisms underlying UHRF1 in progression of renal fibrosis." (PMID 40490444, 2025). "To better understand the role of UHRF1 in progression of renal fibrosis, we performed Reduced Representation Bisulfite Sequencing (RRBS) in nonfibrotic fibroblasts and fibrotic fibroblasts." (PMID 40490444, 2025). "Conversely, fibroblast-specific depletion of UHRF1 alleviated activation of fibroblasts or renal fibrosis both in vivo and in vitro." (PMID 40490444, 2025). "In this study, we observed a significant upregulation of UHRF1 in fibrotic kidneys from two murine models of renal fibrosis." (PMID 40490444, 2025). "In summary, we for the first time demonstrated that UHRF1 was upregulated in activated renal fibroblasts and it was a critical epigenetic regulator for progression of renal fibrosis, utilizing both genetic depletion or pharmacological approaches." (PMID 40490444, 2025). "To ascertain the possible involvement of UHRF1 in renal fibrogenesis, we examined the protein expression and location of UHRF1 in kidneys from two murine models of renal fibrosis." (PMID 40490444, 2025). "Collectively, these results suggest that UHRF1 may be a promising target for mitigating renal fibrosis." (PMID 40490444, 2025). "Our study suggests that UHRF1 is a promising therapeutic target for renal fibrosis." (PMID 40490444, 2025). "As a critical cooperator in DNA methyltransferase 1 (DNMT1)-mediated maintenance of DNA methylation, the role of ubiquitin-like containing PHD and RING finger domains 1 (UHRF1) in renal fibrosis remains unknown." (PMID 40490444, 2025). "Although increasing evidence indicates UHRF1 assists DNMT1 in maintaining DNA methylation, current understanding of its pathological function in renal fibrosis is unclear." (PMID 40490444, 2025).
seminoma (1 paper, 2018). A radiosensitive malignant germ cell tumor found in the testis (especially undescended), and extragonadal sites (anterior mediastinum and pineal gland). "Activating KIT mutations may lock KIT mutant seminoma cells into a PGC-like state in which UHRF1 and DNMT1 expression are suppressed, preventing the development of NSGCT components, which appear to require DNA methylation capacity." (PMID 29898407, 2018).
systemic lupus erythematosus (1 paper, 2024). An autoimmune multi-organ disease typically associated with vasculopathy and autoantibody production. "In systemic lupus erythematosus (SLE), downregulation of UHRF1 led to T follicular helper (Tfh) cell differentiation both in vitro and in vivo." (PMID 38317133, 2024).
teratoma (1 paper, 2018). A non-seminomatous germ cell tumor characterized by the presence of various tissues which correspond to the different germinal layers (endoderm, mesoderm, and ectoderm). "Although a number of phenotypes in Uhrf1 KO cells (i.e. cell death and small teratoma) overlapped with the Dnmt1 KO34, importantly we observed a number of unique features in this Uhrf1 KO study." (PMID 29968706, 2018).
thyroid tumours (1 paper, 2009). "Furthermore, UHRF1 and ITIH5 have a potential therapeutic/prognostic value for aggressive thyroid tumours." (PMID 19809427, 2009).
urinary bladder transitional cell carcinoma (1 paper, 2017). "Recently, expression of the UHRF1 gene was found to be up-regulated in numerous neoplasms, including the urinary bladder transitional cell carcinoma (TCC)." (PMID 28128913, 2017).
cancer (197 papers, 2009 to 2026). A tumor composed of atypical neoplastic, often pleomorphic cells that invade other tissues. "69% of cancer types analyzed associated high expression of UHRF1 with the activation of CellCycle_A." (PMID 40591126, 2025). "The top downregulated gene in the first and third signatures was UHRF1, a multidomain protein that promotes DNA methylation and chromatin modification and is implicated in cell cycle control in several cancers." (PMID 40208872, 2025). "The consistent association between UHRF1 overexpression and adverse outcomes across multiple malignancies underscores its value as a universal target for innovative cancer therapies." (PMID 39051184, 2024). "Thirdly, further studies are required to reveal the roles of UHRF1 PTMs in cancer initiation and progression, and to unveil their associations with crucial biological processes such as cell proliferation, metastasis, and therapeutic resistance." (PMID 38725075, 2024). "These abnormal increases in UHRF1 levels are involved in various disease progression pathways and are associated with a poor clinical outcome, making UHRF1 a promising target for these aggressive forms of cancer." (PMID 39051184, 2024). "This dual role underlines UHRF1′s potential as a therapeutic target in metabolic and epigenetic dysregulation in cancer." (PMID 39684755, 2024). "UHRF1 is highly expressed in the many types of cancers and is implicated in tumorigenesis as an oncogene." (PMID 37628583, 2023). "UHRF1 loss of function induces global hypomethylation, which epigenetically reprograms cancer cells." (PMID 37380646, 2023). "UHRF1 is E3 ubiquitin ligase highly expressed in many human cancers compared to normal tissues, and has been linked to rapid disease progression." (PMID 37407562, 2023). "UHRF1 is overexpressed in different cancers that frequently present RB1 mutations, including lung, breast, bladder, colorectal cancer, and retinoblastoma." (PMID 36068209, 2022). "Since mRNA expression of Cdkn1a and Cdkn2a, which are representative senescence marker genes, is regulated by UHRF1 in lymphocytes and cancer cells, the cellular phenotypes caused by UHRF1 depletion can resemble those of cellular senescence." (PMID 35472067, 2022). "As UHRF1 expression is positively correlated with cancer cell proliferation, it would be interesting to determine how UHRF1 would associate with the prognosis in a specific subtype of AML." (PMID 36302855, 2022). "UHRF1 expression was associated with tumor mutation load and microsatellite instability in different cancer types, and enrichment analysis identified terminology and pathways associated with UHRF1." (PMID 35656341, 2022). "Aberrations in UHRF1 expression were linked with aggressiveness in several cancer types, including ALL." (PMID 36077796, 2022). "Secondly, UHFR1 depletion in cancer cells causes cell cycle arrest in G2/M‐phase, while Jenkins et al20 also show reduction of UHRF1 decreases the growth rates in several tumour cell lines." (PMID 32495469, 2020). "As BRAF and RAS mutations, especially KRAS, broadly occur in cancers, it will be of interest to systematically analyze the relationship between UHRF1/DNMT1 expression and BRAF/RAS mutations." (PMID 30696879, 2019). "Like DNMT1, UHRF1 overexpression has also been found in various cancers and associated with down-regulation of several tumor suppressor genes (TSG) including RB116, p16INK417,18, BRCA119, PPARG20 and KiSS121." (PMID 30696879, 2019). "Loss of function studies showed that UHRF1 depletion decreased cancer cell proliferation and increased apoptotic cell death." (PMID 31245293, 2019). "In alignment with our results, UHRF1 overexpression has been demonstrated to cause tumorigenesis in different cancer types including HCC." (PMID 31482051, 2019). "Consistent with RP11-424C20.2, UHRF1 was also significantly associated with prognosis in the 8 types of cancer." (PMID 31442209, 2019).
cancer (continued). "Loss of UHRF1 function can lead to demethylation and re-expression of epigenetically silenced tumor suppressor genes and can reduce cancer cell growth and survival." (PMID 31105884, 2019). "UHRF1 (ubiquitin-like with PHD and RING finger domains 1) is highly expressed in various cancer cells and its overexpression has been associated with tumor-promoting effects represented by high proliferative potential and inhibition of apoptosis." (PMID 29415984, 2018). "The present findings indicate that thymoquinone induces in cancer cells a fast UHRF1 auto-ubiquitination through its RING domain associated with HAUSP down-regulation." (PMID 29983883, 2018). "Natural products well known for exhibiting anti-cancer properties have been investigated for their ability to cause the downregulation of UHRF1 and re-expression of tumor suppressor gene." (PMID 29899856, 2018). "Jang and coworkers reported that shikonin causes apoptosis by up-regulating p73 and down-regulating UHRF1 in human cancer cells." (PMID 29899856, 2018). "UHRF1 (ubiquitin-like with PHD and RING finger domains 1) is a critical regulator for DNA methylation, and its frequent overexpression in human cancers has been associated with tumor-promoting effects." (PMID 28467809, 2017). "Aberrant overexpression of UHRF1 was detected in many types of cancer tissues and was also associated with poor prognosis of bladder patients." (PMID 28060737, 2017). "Few studies have also predicted UHRF1 as a diagnostic and prognostic marker for various other types of cancers." (PMID 28881702, 2017). "Highly sensitive, non-invasive and cost effective approaches are therefore needed to assess the level of UHRF1 in patients, which can be deployed in diagnostic laboratories to detect cancer and monitor disease progression." (PMID 28881702, 2017). "High UHRF1 mRNA and protein levels are detected in early stages of many tumors suggesting UHRF1 as a valuable diagnostic marker for the timely detection of cancers." (PMID 28881702, 2017). "We recently showed that UHRF1 deficiency contributes to the acquisition of tumor malignancy in a diverse range of cancer cells." (PMID 28584306, 2017). "Next, we determined the level of cancer stem-like cell-related factors in UHRF1-deficient HepG2 cells." (PMID 28584306, 2017). "In contrast herewith, other researchers found that depleting cancer cells of UHRF1 causes cell cycle arrest in G2/M phase." (PMID 28060737, 2017). "Many studies have validated UHRF1 as a powerful diagnostic and prognostic tool to differentially diagnose cancer, predict the therapeutic response and assess the risk of tumor progression and recurrence." (PMID 28881702, 2017). "In this review, we highlight the role of UHRF1 in the epigenetic silencing of TSGs and the molecular mechanisms underlying UHRF1 regulation in cancer cells as well as the increasing importance of UHRF1 as a promising target for anticancer therapy." (PMID 27839516, 2016). "This review describes the molecular mechanisms underlying UHRF1 regulation in cancer and discusses its importance as a therapeutic target to induce the reactivation of TSGs and subsequent apoptosis." (PMID 27839516, 2016). "Overexpression of UHRF1 occurs in many types of cancer, and aberrantly expressed UHRF1 causes cancer cell activation through hyper-methylation of tumor-suppressor genes such as BRCA1, CDKN2A, p73, and RASSF1." (PMID 27072587, 2016). "Exposure of cancer cells to T3 induces a decrease in Sp1 binding to UHRF1 promoter causing its inactivation and subsequent p21 reactivation and cell proliferation inhibition." (PMID 27839516, 2016). "We propose a working model that UHRF1/2 safeguards the fidelity of DNA methylation and suggests that UHRF1/2 overexpression is likely a causal factor for widespread DNA hypomethylation in cancer via suppressing DNMT3A." (PMID 27462454, 2016).
cancer (continued). "Our results reveal widespread co-ordinate deregulated expression of the FOXM1 regulatory network in OAC, including changes in both co-regulators (eg LIN54) and target genes (eg UHRF1) which have potential diagnostic utility in identifying late-stage cancer." (PMID 25889361, 2015). "Previous studies have linked UHRF1 with a number of cancers, including liver, prostate, colon, stomach and blood." (PMID 25765655, 2015). "UHRF1 overexpression is associated with the tumor stages and predicts poor prognoses in various cancers." (PMID 25272010, 2014). "Overexpression of UHRF1 also associated with cancer malignancy indicated by pT and pN factors and survival rate in Japanese cases." (PMID 20517312, 2010). "The association of genes like UHRF1 with multiple pathways indicates its central role in orchestrating complex cellular responses that may contribute to cancer cell survival and proliferation." (PMID 40591126, 2025). "However, aberrant overexpression of UHRF1 causes DNA re-replication, DNA damage, and even genomic instability, which eventually promotes tumorigenesis and cancer progression." (PMID 38725075, 2024). "Beyond its canonical role in DNA methylation, UHRF1 affects metabolic pathways by altering gene expression linked to glycolysis and the tricarboxylic acid cycle, both crucial for meeting the high metabolic demands of proliferating cancer cells." (PMID 39684755, 2024). "The first is that very few mutations of UHRF1 in cancer have been described, suggesting that there may be strong selection for the function of the protein to be maintained." (PMID 35625988, 2022). "What causes the overexpression of UHRF1 in human cancers is unclear." (PMID 33300031, 2021). "UHRF1 inhibition by using pharmacological compounds is associated with the reactivation of various tumor suppressor genes, thus suppressing the proliferation of cancer cells by inducing apoptosis." (PMID 31482051, 2019). "Our results collectively demonstrate that UHRF1 deficiency may play a pivotal role in the malignant alteration of cancer cells." (PMID 28584306, 2017). "Indeed, it was shown that overexpressed UHRF1 causes DNA hypomethylation, a hallmark of cancer cells; instead of normal maintenance of DNA methylation." (PMID 28881702, 2017). "In this study, UHRF1 deficiency led to the expansion of the population of cancer stem-like cells." (PMID 28584306, 2017). "To determine whether UHRF1 deficiency-induced EMT affects the expansion of cancer stem-like cells, we transfected UHRF1-deficient HepG2 cells with Snail siRNA and assessed the mRNA and protein levels of CD133." (PMID 28584306, 2017). "This review highlighted the signalling pathways underlying UHRF1 regulation in cancer cells." (PMID 27839516, 2016). "However, increasing evidence indicates that the expression or overexpression of UHRF1 is associated with a poor prognosis in a variety of cancer types." (PMID 27431502, 2016). "Thus, negative regulation of DNMT3A by overexpressed UHRF1/2 in cancers is likely to be a general mechanism for cancer-associated DNA hypomethylation." (PMID 27462454, 2016). "UHRF1 is overexpressed in many cancers, and UHRF1 overexpression may be a mechanism underlying DNA hypomethylation in cancer cells." (PMID 27507047, 2016). "These clinical studies show that incorporating assays for UHRF1 expression could improve the specificity and sensitivity of current cancer diagnostic tests." (PMID 26884069, 2016).